FRMD1 (FERM domain containing 1)
Synonyms: FLJ00181; DKFZp434O0117; FLJ40260; FLJ22615; bA164L23.1
Tractability: No criterion of Open Targets' tractability assessment is met for any kind of drug.
Gene: Protein-coding gene on chromosome 6 (168,053,095 to 168,101,511, reverse strand). Ensembl gene ENSG00000153303.
Subcellular location (Human Protein Atlas): Actin filaments; Cytosol
Gene Ontology:
Molecular function: protein binding; protein sequestering activity
Biological process: positive regulation of hippo signaling
Cellular component: cell-cell junction; plasma membrane
Genetic constraint (gnomAD): Loss-of-function variants: 44 observed, 45.73 expected, observed/expected ratio (o/e) 0.96, 90% interval 0.75 to 1.24. The upper end of that interval is the gene's LOEUF score, 1.24, which puts it in group 5 of 6, group 1 being the genes least tolerant of losing a copy. Missense variants: 690 observed, 678.73 expected, observed/expected ratio (o/e) 1.02, 90% interval 0.95 to 1.08. Synonymous variants: 313 observed, 274.89 expected, observed/expected ratio (o/e) 1.14, 90% interval 1.04 to 1.25.
Homologues: Orthologues: chimpanzee FRMD1 (60% identical), dog FRMD1 (55% identical), macaque FRMD1 (54% identical), pig FRMD1 (53% identical), zebrafish FRMD1 (39% identical), Drosophila melanogaster ex (26% identical), zebrafish si:ch73-205h11.1 (26% identical), Caenorhabditis elegans frm-7 (21% identical).
Diseases named in the same sentence as FRMD1 in open-access papers:
FRMD1 is named in the same sentence as 5 diseases in open-access papers, as found by Europe PMC text mining. Sharing a sentence is not in itself a finding about the gene and the disease. The quoted sentences say what the papers report.
adult T-cell leukemia (1 paper, 2025). "Dysregulation of FRMD1 has been linked to adult T-cell leukemia/lymphoma." (PMID 40869915, 2025).
tumor (1 paper, 2021). "TEAD3 is a transcription factor and FRMD1 is an activating transcription factor binding which have important functions in the Hippo signaling pathway, a pathway involved in tumor suppression by limiting proliferation and boosting apoptosis." (PMID 34446027, 2021).
FRMD1 also shares sentences with these, for which no sentence is quoted: angiosarcoma (1 paper); cancer (1); lymphoma (1).